MMP3 (matrix metallopeptidase 3)
Diseases named in the same sentence as MMP3 in open-access papers (continued):
Sharing a sentence is not in itself a finding about the gene and the disease.
melanoma (continued). "The relative expression level of the hub genes was reverified in melanoma cell lines, and showed that HIF1A, IL1B, HMOX1, MMP3, CDKN2A and TIMP1 were upregulated, while PTEN, PRKCA, ATF3 and BRAF were downregulated in melanoma samples." (PMID 36226170, 2022). "IL-1β induced the migration of melanoma cells; however, this migration was attenuated by UK356618, an MMP-3 inhibitor." (PMID 36445856, 2022). "ABL1 promotes melanoma invasion through STAT3-dependent MMP1 expression, while ABL2 promotes melanoma invasion by increased expression of MMP-1, MMP-3, and MT1-MMP independently of STAT3." (PMID 34022881, 2021). "This indicates that Tspan8+ melanoma cells, once invading the dermis, acquire the capability of expressing the precursor forms of MMP-9 and MMP-3, which were previously provided by the keratinocytes when situated in the epidermis." (PMID 32455575, 2020). "Treating the melanoma cells with rCTII substantially inhibited the transforming growth factor-beta (TGF-β)–SMAD signaling pathway and down-regulated the expression of MMP-3 and miR-214 as well." (PMID 33167431, 2020). "Surprisingly, MMP-9 and MMP-3 transcripts were increased in invading melanoma cells that have penetrated the DEJ, in comparison to melanoma cells still in contact with the DEJ." (PMID 32455575, 2020). "The qRT-PCR was performed to evaluate the expression levels of matrix metallopeptidase 3 (MMP-3), SMAD2, SMAD3, caspase-8, caspase-9, and miR-214 in order to reveal the rCTII-induced signaling pathways in melanoma." (PMID 33167431, 2020). "Although the ZO-1 expression recovered after inhibition of MMP3 with PD166793, moderate inhibition of melanoma brain metastasis was observed." (PMID 30616691, 2019). "In this study using B16-BL6 mouse melanoma cells, we found that LRSKSRSFQVSDEQYPDATDE (LRS-TDE) peptide in the C-terminal fragment of OPN cleaved by MMP-3/7 binds to α9β1 integrin." (PMID 25545242, 2014). "The significant inhibition in IL-1β-mediated-MMP-3 mRNA expression was observed in the cells pretreated with TPCA-1 (10 μM) for 1 h, suggesting that the activation of NF-κB is involved in MMP-3 mRNA expression in IL-1β-stimulated canine melanoma cells." (PMID 36445856, 2022). "To confirm the contribution of NF-κB to MMP-3 mRNA expression mediated by IL-1β, we investigated whether IL-1β induced the mRNA expression of MMP-3 in p65/RelA or p105 knockdown melanoma cells." (PMID 36445856, 2022). "In conclusion, we demonstrated that IL-1β induces the activation of NF-κB p65/RelA, but not p105, which contributes to IL-1β-induced MMP-3 expression in canine melanoma cells." (PMID 36445856, 2022). "The roles of KCNE4 in chemokine production and cell adhesion were examined using primary lymphatic endothelial cells, and demonstrated that Ccl17 and Ccl19, which are involved in melanoma metastasis, were upregulated by KCNE4, as well as Mmp3 matrix metalloproteinase." (PMID 35915077, 2022). "A high expression of MMP-3 was reported to correlate with the tumor size of the melanoma in the patient, suggesting the contribution of MMP-3 to the processes is involved in the invasiveness of malignant melanomas." (PMID 36445856, 2022). "Moreover, MMP3 has been highly expressed in melanoma and in ECM around blood vessels, proposing a significant role to remodeling induced by the aggressive melanoma progression." (PMID 33809973, 2021). "Similarly, ABL kinases drive melanoma cell invasion by inducing expression of matrix metalloproteinases MMP-1, MMP-3, and MT1-MMP." (PMID 34022881, 2021). "The current study has demonstrated that rCTII might substantially stimulate the apoptosis pathways, especially the intrinsic pathway, inhibit the expression of mir-214 and MMP-3, and suppress the TGF-β pathway via down-regulating SMAD2 and SMAD3 in melanoma." (PMID 33167431, 2020). "This was consistent with the immunodetection of MMP-9 and MMP-3 in melanoma cells located into the dermis, but not those localized in the epidermis." (PMID 32455575, 2020).
melanoma (continued). "Melanoma cells express several members of the Ca2+/calcineurin-regulated NFAT family of transcription factors, that lead to melanoma survival via interleukin-8 (IL8) and metalloproteinase-3 (MMP-3) expression." (PMID 33091721, 2020). "MMP3 can be regulated by NFAT1 and promote melanoma tumor growth and lung metastasis." (PMID 33042984, 2020). "ETS1 also regulates genes involved in melanoma cell invasiveness: MMP1, MMP3 and integrin-β3." (PMID 26885752, 2016). "However, IL-1β failed to mediate the expression of MMP-3 mRNA in p65/RelA-knockdown melanoma cells but not in p105-knockdown cells." (PMID 36445856, 2022). "However, in melanoma cells treated with UK356618 (50 nM), IL-1β failed to mediate cell migration, implying that MMP-3 is involved in IL-1β-induced melanoma cell migration." (PMID 36445856, 2022). "Overall, our data show that Tspan8+ melanoma cells surrounded by keratinocytes maintained lower TIMP-1 level when compared to melanoma cells juxtaposed without contacts with keratinocytes, thus favoring proMMP-9 activation by the fully active MMP-3, in a Tspan8-dependent manner." (PMID 32455575, 2020). "Because MMP3 activates the collagenases MMP1, MMP8 and MMP13 that are capable of degrading collagen types I, II, III, V and IX as well as native fibrillary collagen which is crucial for melanoma metastasis, we tested for MMP3 secretion by performing western blot analyses." (PMID 31728131, 2019). "This study reveals the genes C7, MMP3, KRT14, LOC642587, CASP7, S100A7 and miRNAs hsa-mir-205 and hsa-mir-203b as the key genomic features that may substantially contribute to the oncogenesis of melanoma." (PMID 31673075, 2019). "MMP-3 activation status was examined by Western blot and we observed a 52 kDa band corresponding to the molecular weight of proMMP-3 in all types of cultures, except the culture with melanoma cells alone, indicating that proMMP-3 is generated by keratinocytes and not melanoma cells." (PMID 32455575, 2020). "MMP-3 and MMP-9 were completely absent.Melanoma: All three MMPs were highly expressed, exhibiting intense cytoplasmic and nuclear localization." (PMID 42158425, 2026).
periodontitis (46 papers, 2007 to 2025). An acute or chronic inflammatory process that affects the tissues that surround and support the teeth. "This study aimed to explore the correlation between the Matrix Metalloproteinase-3 (MMP-3) 1171 5A/6A gene polymorphism and susceptibility to Chronic Periodontitis (CP)." (PMID 39712510, 2024). "Meta-analysis of the Association between MMP-3 1171 5A6A Gene Polymorphism and Susceptibility to Chronic Periodontitis." (PMID 39712510, 2024). "Collagenases (MMP-1, -8, and -13), gelatinase (MMP-2 and -9), and stromelysin-1 (MMP-3) have all been implicated in periodontitis." (PMID 37110385, 2023). "On the other hand, a meta-analysis involving an excess of 6000 subjects suggested that MMP-9 reduced the risk of periodontitis, whereas MMP-3 and -8 increased the risk of periodontitis." (PMID 34444764, 2021). "Several studies have investigated the effect of the MMP-3 -1171 5A/6A polymorphism on the predisposition to periodontitis in different populations." (PMID 34684209, 2021). "Both polymorphisms of MMP-3 have been investigated in patients with periodontitis from various populations, including Caucasian, Asian, and Latin American societies, to analyze the influence of SNPs on MMP-3 enzyme regulation." (PMID 34684209, 2021). "The current literature evidently suggests that the influence of the MMP-3 -1171 5A/6A polymorphism on periodontitis susceptibility, in either different races or the same race, is conflicting." (PMID 34684209, 2021). "This study aims to investigate the effect of MMP-3 -1171 5A/6A polymorphism and the GCF levels of MMP-3 in a group of Turkish periodontitis patients." (PMID 34684209, 2021). "MMP3 (matrix metalloproteinase 3) is implicated in the progression of chronic periodontitis and can degrade the periodontal tissue matrix." (PMID 33869630, 2021). "This study examined the link between MMP-3 -1171 5A/6A polymorphism and the risk of periodontitis at a slow or rapid rate." (PMID 34684209, 2021). "Among these SNPs, the rs522616 and rs650108 polymorphisms of MMP-3 have been identified in different diseases, such as chronic periodontitis and sporadic brain arteriovenous malformation." (PMID 29312574, 2017). "A previous study reported an association between the MMP-3 rs650108 polymorphism and chronic periodontitis in a Brazilian population." (PMID 28676856, 2017). "Subgroup analyses suggested that the MMP-9-1562 C/T polymorphism reduced chronic periodontitis susceptibility and MMP-3-1171 A5/A6polymorphism increased chronic periodontitis susceptibility." (PMID 27095260, 2016). "The −1171 5A/6A variant, a well-characterized insertion/deletion polymorphism in the promoter region of MMP-3 gene, is considered to be functionally involved in the process of periodontitis." (PMID 27194818, 2016). "Our results provided some evidence to support an elevated risk between periodontitis susceptibility and MMP-3-1171 A5 allele and MMP-8-799 T allele, and a reduced risk between periodontitis susceptibility and MMP-9-1562 T allele." (PMID 27095260, 2016). "The relationship between the MMP3 -1171 5A/6A polymorphism (rs35068180) and periodontitis has been widely studied." (PMID 26123623, 2015). "Our results suggest an association between the transcriptionally more active 5A allele and periodontitis, substantiating previous functional findings regarding the MMP3 rs35068180 variant." (PMID 26123623, 2015). "Our meta-analysis was based on seven case–control studies that focused on the link between MMP3 -1171 5A/6A polymorphism and periodontitis risk and included a total of 1,213 cases and 1,831 controls." (PMID 26123623, 2015). "In this report, we first analysed the effect of MMP3 -1171 5A/6A polymorphism on two forms of periodontitis." (PMID 26123623, 2015). "The relationship between MMP3 -1171 5A/6A polymorphism and periodontitis has been widely investigated." (PMID 26123623, 2015).
periodontitis (continued). "Over the past decade, many genetic association studies have been conducted to evaluate the association between MMP3 -1171 5A/6A polymorphism and the risk of periodontitis." (PMID 26123623, 2015). "However, in patients with chronic periodontitis associated with type 2 diabetes, the levels of both MMP-3 and MMP-14 were significantly higher than in healthy or non-diabetic inflamed gingival tissues." (PMID 40075856, 2025). "The study’s findings suggest that smoking habits may interact with the MMP-3 gene polymorphism to influence chronic periodontitis susceptibility." (PMID 39712510, 2024). "Treatment of both healthy and periodontally diseased gingival fibroblasts with pan-HDACi or HDAC3/6i prior to P. gingivalis infection significantly reduced the induction of a subset of inflammatory mediators (CCL2, CCL5, CXCL10, IL1B, COX2 and MMP3) implicated in periodontitis." (PMID 36291079, 2022). "Our findings suggest that MMP-3 is a biomarker associated with periodontitis, and its expression might be dependent on several other immunological mechanisms as well as the genetic polymorphisms, for Turkish individuals." (PMID 34684209, 2021). "Likewise, MMP3 abundantly produced in periodontitis was also found to be associated with neuroinflammation via activating microglial cells, as well as participating in the BBB breakdown through the proteolysis of fibronectin and type IV collagen." (PMID 33869630, 2021). "Therefore, we performed a meta-analysis to investigate the potential association of MMP3 -1171 5A/6A polymorphism with the risk of periodontitis." (PMID 26123623, 2015). "This suggests that SGE ameliorates periodontitis by inhibiting MMP-3, -8, -9, and -13 expressions in PDLF cells." (PMID 36830029, 2023). "Genetic polymorphisms of matrix metalloproteinase-3 (MMP-3) and vitamin D receptor (VDR) predispose an adolescent to periodontitis." (PMID 35757444, 2022). "The sensitivity and specificity of MMP-3 for predicting periodontitis were 81.8% and 55.5%, respectively." (PMID 35562715, 2022). "It is challenging to suggest an absolute value of MMP-3 for predicting periodontitis, as the value of making a clinical diagnosis using an ROC curve varies depending upon the measurement environment and target." (PMID 35562715, 2022). "Exploration of available transcriptomic datasets revealed C4A, C4B, CXCL12, FCGR3A, IL1B, and MMP3 as the top candidate molecular linkage genes between periodontitis and AD." (PMID 33869630, 2021). "Another study conducted in a Turkish sample population also showed increased levels of MMP-3 in the GCF of patients with both aggressive and chronic periodontitis, in the presence of periodontal–pathogenic microorganisms." (PMID 34684209, 2021). "The current results of studies on the MMP-3 promoter gene variation, on the other hand, have revealed poor outcomes in determining its relation to periodontitis." (PMID 34684209, 2021). "Six genes C4A, C4B, CXCL12, FCGR3A, IL1B, and MMP3 were identified as the most significant crosstalk genes linking chronic periodontitis and Alzheimer's disease." (PMID 33869630, 2021). "The present work aims to study the 5A/6A single nucleotide polymorphism at the -1171 location in the MMP-3 promoter gene and its effect on the MMP-3 expression in the GCF in a Turkish population diagnosed with periodontitis." (PMID 34684209, 2021). "The degree of suppression of IL8, IL1B, CCL2, CCL5, MMP3, and COX2 caused by I-BET151 or JQ1 in P. gingivalis-infected GFs from periodontitis patients was comparable to that observed in healthy donor GFs." (PMID 31114581, 2019). "MMP-3 (stromelysin) and MMP-9 (gelatinase B) have been strongly associated with the progression of periodontitis." (PMID 29321009, 2018). "A meta-analysis involving in excess of 6000 individuals established that MMP-9-753 C/T polymorphism reduced the risk of chronic periodontitis, while MMP-3-1171 5A/6A and MMP-8-799 C/T polymorphisms increased the risk of chronic periodontitis." (PMID 28218665, 2017).
periodontitis (continued). "Single nucleotide polymorphisms (SNPs) at IL-1β, MMP3, TGF-β1, and GDF5 have been associated with risk of a wide variety of diseases, such as keratoconus, chronic periodontitis, and lumbar disc degeneration." (PMID 28676856, 2017). "In the present meta-analysis, we aggregated data from published studies to estimate genetic associations between MMP gene, namely MMP-2-753 C/T, MMP-3-1171 A5/A6, MMP-8-799 C/T, and MMP-9-1562 C/T polymorphisms, and periodontitis susceptibility." (PMID 27095260, 2016). "In different sites from the same periodontitis patients (P2: P3, P7: P8, and P9: P10), it was clearly noticeable that MMP3, MMP13, and LBP expressions differ in a site-specific manner." (PMID 27531006, 2016). "The results were similar to MMP-3-1171 A5/A6 and MMP-2-753 C/T polymorphisms for periodontitis susceptibility." (PMID 27095260, 2016). "Genetic polymorphisms of pro‐inflammatory mediators MMP3, CD28, and VDR seem to link to initial periodontitis." (PMID 29744169, 2016). "The results based on 2,724 periodontitis patients and 3,438 controls showed that MMP-9-1562C/T, MMP-3-1171 A5/A6, and MMP-8-799C/T polymorphisms were associated with periodontitis susceptibility." (PMID 27095260, 2016). "Our main finding is that PTPα plays a central role in the connective tissue destruction of ligature-induced periodontitis possibly through the maintenance of focal adhesion dynamics in fibroblasts that enable IL-1β signaling and MMP-3 expression." (PMID 23940616, 2013). "In periodontitis, MMP-3 is present at increased levels in active disease sites compared to inactive or healthy sites, and the levels are correlated with clinical parameters and associated with progression of the disease." (PMID 17319946, 2007). "The concentration of MMP-3 in saliva reflects periodontal health status, so this outcome demonstrates that PACs provide additional beneficial effects on clinical and immunological parameters in the treatment of periodontitis." (PMID 41002732, 2025). "MMP-1 and MMP-3 have been demonstrated to play an important role in periodontitis." (PMID 37445663, 2023). "A goal of this study was to determine whether MMP-3 might be considered as a biomarker of periodontitis." (PMID 36167610, 2023). "We have hypothesized that in the Turkish population diagnosed with periodontitis, the promoter polymorphism of MMP-3 at the -1179 location is responsible for the high MMP-3 levels in the GCF that lead to exacerbated periodontal tissue destruction." (PMID 34684209, 2021). "In addition, polymorphisms in MMP-1, MMP-3, MMP-8, and MMP-9 are associated with chronic periodontitis susceptibility." (PMID 33477537, 2021). "MMP-3 (stromelysin-1) is a notable proteolytic enzyme among the other MMP types due to its central role in activating the latent MMP types such as MMP-7, MMP-8, MMP-9, and MMP-13, and it has been claimed that MMP-3 has a pivotal function in the initiation of collagen disintegration in periodontitis." (PMID 34684209, 2021). "Considering that gingival tissues-derived MMP-3 contributes to the progression of adult periodontitis by activating MMP-8 and MMP-9 derived from crevicular fluid neutrophil, increased expression of MMPs would be responsible for age-related periodontal inflammation." (PMID 33477537, 2021). "MMP-3 is a broad-spectrum MMP and serves as a pivotal activator of latent MMPs, and it has been linked to tissue destruction associated with chronic inflammatory disease such as periodontitis." (PMID 29054963, 2017). "Moreover, many molecular epidemiological studies has been conducted to investigate the association between MMP-3-1171 A5/A6, MMP-8-799 C/T, and MMP-2-753 C/T polymorphisms and periodontitis susceptibility." (PMID 27095260, 2016). "Matrix metalloproteinase-3 (MMP3) plays a key role in tissue degradation in periodontitis." (PMID 26123623, 2015). "The role of MMP3 in the pathogenesis of periodontitis has been widely investigated." (PMID 26123623, 2015).